CACNA1S (calcium voltage-gated channel subunit alpha1 S)
Diseases named in the same sentence as CACNA1S in open-access papers:
CACNA1S is named in the same sentence as 85 diseases in open-access papers, as found by Europe PMC text mining. Sharing a sentence is not in itself a finding about the gene and the disease. The quoted sentences say what the papers report.
hypokalemic periodic paralysis (19 papers, 2015 to 2026). Hypokalemic periodic paralysis (hypoPP) is characterized by episodes of muscle paralysis lasting from a few to 24-48 hours and associated with a fall in blood potassium levels. "Familial hypokalemic periodic paralysis (HypoPP) is a rare autosomal dominant skeletal muscle channelopathy most commonly caused by pathogenic variants in the CACNA1S gene." (PMID 42099363, 2026). "Mutations in the CACNA1S gene, which encodes a voltage-dependent calcium channel, cause hypokalemic periodic paralysis, type 1 [MIM: 170400], most classically characterized by episodic weakness with low serum potassium levels." (PMID 35996156, 2022). "Hypokalemic periodic paralysis is an autosomal dominant, rare disorder caused by variants in the genes for voltage-gated calcium channel CaV1.1 (CACNA1S) and NaV1.4 (SCN4A)." (PMID 34120654, 2021). "Of all individuals meeting the diagnostic criteria for hypokalemic periodic paralysis, approximately 60 % have mutations in the calcium channel CACNA1S gene, 20 % in the sodium channel SCN4A gene and 3.5 % in the potassium KCNJ18 gene." (PMID 27682153, 2016). "In the mycobacterium tuberculosis infection, calcium homeostasis is significantly related to the expression of CACNA1S, and the changes in CACNA1S expression level increase susceptibility to malignant hyperthermia, hypokalemic periodic paralysis, and congenital muscle disease (35, –, 37)." (PMID 40029616, 2025). "In addition, four families with muscle biopsies showing characteristic intermyofibrillar network and centralized nuclei or core-like structures had pathogenic variants in CACNA1S, a gene usually associated with hypokalemic periodic paralysis or malignant hyperthermia." (PMID 38982518, 2024). "Hypokalemic periodic paralysis (HypoPP) is a rare genetic disease associated with mutations in CACNA1S or SCN4A encoding the voltage-gated Ca2+ channel Cav1.1 or the voltage-gated Na+ channel Nav1.4, respectively." (PMID 37139703, 2023). "Mutations in the CACNA1S, RYR1, SCN4A gene have been reported to be associated with hypokalemic periodic paralysis (HOKPP) in humans." (PMID 35158718, 2022).
Malignant hyperthermia (16 papers, 2011 to 2025). Malignant hyperthermia is characterized by a rapid increase in temperature to 39-42 degrees C. Malignant hyperthermia may occur in response to either inhalational anesthetics such as halothane, to muscle relaxants such as succinylcholine, or to exercise. "Mutations have been identified in CACNA1S in patients with malignant hyperthermia and primary periodic paralysis." (PMID 34193198, 2021). "The third SNP, rs2281845, on chromosome 1q32.1 is just upstream of CACNA1S (voltage-dependent calcium channel, L type), a gene subject to mutation screens for malignant hyperthermia and periodic paralysis." (PMID 21931568, 2011). "For some disorders, including CACNA1S-related malignant hyperthermia (MH), setting an appropriate DAFT is complicated by disease attributes." (PMID 41000626, 2025). "Mutations in CACNA1S are mostly related to dominant inheritance, causing hypokalemic periodic paraplegia type 1 (MIM 170400) and malignant hyperthermia (MIM601887)." (PMID 36292632, 2022). "Our data show that the three genes currently associated with malignant hyperthermia (RYR1, CACNA1S and STAC3) are all misregulated in groups 1 and 3, but not group 2." (PMID 36282542, 2023).
periodic paralysis (16 papers, 2011 to 2025). "Interestingly also in CACNA1S gene mutation, which is another channel disorder, namely hypokalemic periodic paralysis, gender differences based on reduced penetrance in women and full in men were identified." (PMID 32733356, 2020). "We obtained a Japanese nationwide case series of 119 index patients (108 men and 11 women) clinically suspected of periodic paralysis, and a gene panel analysis, targeting CACNA1S, SCN4A, and KCNJ2 genes, was conducted." (PMID 36779057, 2023). "We propose Nitrendipine, a potent blocker of the calcium channel (CACNA1S), as a treatment for Hypokalemic periodic paralysis." (PMID 27196054, 2016).
channelopathies (8 papers, 2019 to 2025). "Mutations in genes encoding the subunit of L-type voltage-dependent calcium channel Cav1.1 (CACNA1S) and skeletal muscle sodium voltage-gated channel Nav1.4 (SCN4A) are responsible for channelopathies observed in HPP." (PMID 39897933, 2025).
Myotonia (7 papers, 2014 to 2025). An involuntary and painless delay in the relaxation of skeletal muscle following contraction or electrical stimulation. "Mis‐splicing of the CaV1.1 calcium channel encoded by CACNA1S has also been linked with exacerbated myotonia in these model systems." (PMID 39450929, 2024). "For instance, in DM1-affected skeletal muscle, mis-splicing of chloride ion channel CLCN1 causes myotonia and misregulated splicing of Ca2+ pump CACNA1S and insulin receptor INSR transcripts likely contribute to muscle weakness and insulin resistance, respectively." (PMID 36499107, 2022). "Mis-spliced ion channels associated with defects in skeletal muscle excitation-contraction coupling and myotonia – CACNA1S e29 and CLCN1 e7a – frequently ranked among the top 3 most significantly correlated events for ADF, HGS, and 10MRW." (PMID 39836447, 2025). "Particularly, missplicing of muscle chloride channel (CLCN1), insulin receptor (INSR), bridging integrator 1 (BIN1) and calcium channel voltage-dependent L type alpha 1S subunit (CACNA1S) results in myotonia, insulin resistance and muscle weakness, respectively, constituting key hallmarks of DM." (PMID 25183524, 2014).
congenital myopathy (6 papers, 2015 to 2023). "One of these is CACNA1S, which is recognized as the cause of Dihydropyridine Receptor Congenital Myopathy." (PMID 37510268, 2023). "Another example of patients with a recently identified phenotype-genotype association concerned two adult patients (I303 and I164) with mild congenital myopathy due to pathogenic variants in the CACNA1S gene." (PMID 34440373, 2021). "Different phenotypes were reported in patients with mutations in CACNA1S, such as hypoPP1, congenital myopathy, and malignant hyperthermia susceptibility (MHS)." (PMID 34208776, 2021).
Arrhythmia (2 papers, 2021 to 2023). Any cardiac rhythm other than the normal sinus rhythm. "In particular, RyR2, CACNA1S, and CACNA1S were highly enriched and identified as prominent targets in arrhythmia treatment among these three pathways." (PMID 37598173, 2023).
arthrogryposis (2 papers, 2022). A rare, non-progressive congenital disorder characterized by multiple joint contractures which are present at birth. "These four altered genes (TPM2, KLHL30, KLHL40, and CACNA1S), detected using WES, are expressed in the muscle and have been associated in the literature with akinesia, NM, and arthrogryposis." (PMID 36292632, 2022). "For variants in genes critical to excitation-contraction coupling (CACNA1S, SCN4A, STAC3), oedema may present as early as 15–18 w, simultaneously accompanied by arthrogryposis." (PMID 36761691, 2022).
breast carcinoma (2 papers, 2016 to 2022). "Therefore, L-type calcium channels, in particular CACNA1S and CACNA1D are expressed in breast cancer and contribute to filopodia formation and cancer cell invasion." (PMID 27910855, 2016). "Of the L-type calcium channel α1 subunits, expression of CACNA1D, CACNA1S, but not CACNA1C, was detected in MDA-MB-231 cells at the mRNA level (CACNA1F was not tested as it appeared to be often downregulated in breast cancer clinical samples)." (PMID 27910855, 2016).
HyperPP (2 papers, 2020 to 2024). "Among them, 3 families with HypoPP and 1 family with HyperPP carried mutations in the SCN4A gene (31 patients), while 1 carried a mutation in the CACNA1S gene (7 patients)." (PMID 38609989, 2024).
Hypertension (2 papers, 2021 to 2023). The presence of chronic increased pressure in the systemic arterial system. "Nifedipine is a dihydropyridine L-type calcium channel blocker used to treat hypertension; its target gene (CACNA1S) and primary enzyme genes (CYP1A1 and CYP2A6) all had deleterious variants in our population." (PMID 35280256, 2021).
myotonic dystrophies (2 papers, 2017 to 2018). "Nevertheless, our findings are consistent with a recent study, which suggested that DMPK is implicated in myotonic dystrophy by its dysregulation of MBNL1 and CELF1 mediated alternative splicing of the L-type calcium channel CACNA1S." (PMID 28152551, 2017).
Vacuolar Myopathy (2 papers, 2021 to 2022). "Muscle biopsy revealed a vacuolar myopathy, and genetic testing identified a pathogenic variant in the CACNA1S gene, locus 1q32.1 [c.3716G> A (p.Arg1239His), heterozygous state]." (PMID 34804722, 2021).
acute myeloid leukaemia (1 paper, 2016). "The CaV1.1 gene (CACNA1S) is reportedly overexpressed in cancer compared with normal tissues in acute myeloid leukaemia, brain desmoplastic medulloblastoma and neuroectodermal tumours." (PMID 27342111, 2016).
age-related macular degeneration (1 paper, 2012). Age-related loss of vision in the central portion of the retina (macula), secondary to retinal degeneration. "Two of these genes have been related to ophthalmologic disorders, including age related macular degeneration (HMCN1) and keratoconus (VSX1) and several have been related to neurologic disorders (IKBKAP, SGCG, SACS, ARHGEF10, and CACNA1S)." (PMID 23139751, 2012).
basal cell carcinoma (1 paper, 2022). A carcinoma involving the basal cells. "The expression of CACNA1S, ATP2A1, RYR1, and MYLK3 was upregulated in MAC compared with normal sweat glands and syringoma tumor cells and was generally negative in trichoepithelioma and infundibulocystic type basal cell carcinoma." (PMID 35509066, 2022). "We demonstrated that the CACNA1S, MYLK3, RYR1, and ATP2A1 proteins were more highly expressed in MAC tumor cells than in normal sweat glands and syringoma, while were generally negative in tumor cells of trichoepithelioma and basal cell carcinoma, infundibulocystic type." (PMID 35509066, 2022).
cardiac hypertrophy (1 paper, 2020). "Cardiac hypertrophy is associated with alterations in calcium handling and hence, it is reassuring that genes encoding for proteins involved in calcium handling and signaling (CACNA1D, CACNA1G, CACNA1S or CASC2) also show differential expression at all time points in our model." (PMID 32878883, 2020).
epilepsy (1 paper, 2023). A brain disorder characterized by episodes of abnormally increased neuronal discharge resulting in transient episodes of sensory or motor neurological dysfunction, or psychic dysfunction. "Therefore, the present recorded high expression of mRNA of both CACNA1S Ca2+ (Cav1.1) and NMDA confirmed NMDA receptor-mediated elevations in [Ca21] during the induction of epilepsy." (PMID 37763219, 2023).
heart failure (1 paper, 2025). Inability of the heart to pump blood at an adequate rate to meet tissue metabolic requirements. "Analysis of gene function revealed that CACNA1S, ATP2A3, and MYH7 were involved in cardiac muscle contraction and adrenergic signaling in cardiomyocytes, both of which are associated with heart failure and other diseases." (PMID 40029616, 2025).
hyperthyroidism (1 paper, 2023). Overactivity of the thyroid gland resulting in overproduction of thyroid hormone and increased metabolic rate. "The corresponding mutated genes set that has common effects on hyperthyroidism in children included IGF1, CACNA1S, MYH7, IL6, TTN, CACNB2, LAMA2, and DMD." (PMID 37876543, 2023).
hypertrophic cardiomyopathy (1 paper, 2023). A condition in which the myocardium is hypertrophied without an obvious cause. "“Hypertrophic cardiomyopathy” in the signal pathway was followed with the p.adjust value of 1.10×10-3 and the corresponding collective action gene set with mutations included 8 genes: IGF1, CACNA1S, MYH7, IL6, TTN, CACNB2, LAMA2, DMD." (PMID 37876543, 2023).
muscle atrophy (1 paper, 2020). The loss of muscle tissue due to inactivity or disease. "In one such family, HypoPP has been linked to the known R528H variant in CaV1.1, suggesting the possibility that the CACNA1S gene may represent a genetic risk factor for progressive muscle atrophy." (PMID 32222817, 2020).
preeclampsia (1 paper, 2024). Preeclampsia is a hypertensive disorder of pregnancy that is characterized by new-onset hypertension with proteinuria presenting after 20 weeks of gestation, and depending on mild or severe forms may initially present with severe headache, visual disturbances, and hyperreflexia. "Meanwhile, CACNA1S was the top gene mediating the causal direction from ME3 to preeclampsia." (PMID 38666214, 2024).
Vertigo (1 paper, 2024). An abnormal sensation of spinning while the body is actually stationary. "Mutations in ion channel genes (HyperPP: SCN4A, HypoPP: SCN4A/CACNA1S) are the main cause of both diseases, and acetazolamide can reduce vertigo attacks to some extent in MD; hence, MD may be related to ion channel-related dysfunction." (PMID 39429303, 2024).
myopathy (15 papers, 2015 to 2024). A disease of the muscle in which the muscle fibers do not function properly. "Through the collection of all the patients described in the literature, our review has better defined the complex clinical phenotype of CACNA1S-related myopathy." (PMID 37510268, 2023). "In these cases, a clinical diagnosis was upheld with possible co-existing MYH7 and CACNA1S-related myopathy." (PMID 29970176, 2018). "In conclusion, in this 3-year follow-up study, we found that HypoPP-causing variants in CACNA1S can cause a progressive myopathy in both patients with and without attacks of paralysis." (PMID 37656291, 2023). "Our review also highlighted the wide heterogeneity within CACNA1S-related myopathies." (PMID 37510268, 2023). "Loss of function mutations observed in the CACNA1S first domain (p.F275L) and the nearby pore forming subdomain resulted in myopathy, a disease that is clearly not present in the affected individuals of our cohort." (PMID 30319441, 2018). "For example, repurposing of therapies targeting excitation–contraction coupling and Ca2+ homeostasis can be envisaged for CACNA1S or the SOCE pathway, or anti-oxidant modulators for PYROXD1-related myopathy." (PMID 38982518, 2024).
cancer (5 papers, 2016 to 2022). A tumor composed of atypical neoplastic, often pleomorphic cells that invade other tissues. "Importantly, individual silencing of CACNA1D or CACNA1S gene expression using multiple siRNA oligos decreased both filopodia formation and cancer cell invasion, indicating that CACNA1D and CACNA1S are likely to synergistically support filopodia formation and cancer cell invasion in MDA-MB-231 cells." (PMID 27910855, 2016). "We thus note a theme already observed here, in that in addition to their involvement in ASDs, both CACNA1s and PRKCB are reported to be involved in both cancer development and metabolism-related issues." (PMID 27055244, 2016). "Hovewer, this phosphosite does not appear to be conserved in the CACNA1D or CACNA1S isoforms identified in our study as drivers of filopodia formation in cancer cells." (PMID 27910855, 2016).
tumor (4 papers, 2014 to 2023). "The four candidate genes (CACNA1S, ATP2A1, RYR1, and MYLK3) of Ca2+ signaling have special functions in tumor progression." (PMID 35509066, 2022). "VCGG channels, including CACNA1C, CACNA1D, CACNA1F, CACNA1E, CACNA1A, CACNA1G, CACNA1I, showed significantly higher expression in KIRC than normal cases, whereas CACNA1S and CACNA1H showed higher expression in normal than tumor cases." (PMID 36588677, 2022).
cardiovascular diseases (3 papers, 2014 to 2025). "These regions contain genes associated with calcium channels (CACNA1S), renin catalysis (REN), blood groups (ABO), apolipoprotein (APOA5), and cardiovascular diseases (RASGRP1)." (PMID 25519368, 2014).
infection (3 papers, 2015 to 2022). The state of being infected such as from the introduction of a foreign agent such as serum, vaccine, antigenic substance or organism. "Similarly, LUJV infection was inhibited following the knockdown by siRNA of either CACNA1S or CACNA2D2, indicating that VGCC is critical for LUJV entry." (PMID 34925303, 2021). "Therefore, in this study we investigated the regulation of CACNA1S expression in murine macrophages in the context of M. tb antigenic stimulation and live infection." (PMID 25915405, 2015). "Therefore, in this report, we investigated the ability of Rv2463 and M. tb live infections in regulating CACNA1S expression and the role of innate receptors and downstream signaling molecules thereof." (PMID 25915405, 2015). "For time series analysis, the DEGs of JEG-3 cells in placenta tissue after infection for 3 h, 12 h and 24 h were evaluated, which involved only 2 overlapped DEGs including DLG4 and CACNA1S." (PMID 36209057, 2022). "Furthermore, the siRNA knockdown of CACNA1S effectively blocked infection by MACVpv, but not by VSVpv." (PMID 34925303, 2021).
CACNA1S also shares sentences with these, for which no sentence is quoted: Hypokalemia (4 papers); Andersen-Tawil syndrome (3); Central core disease (3); Duchenne muscular dystrophy (2); hypokalemic periodic paralysis, type 1 (2); muscular dystrophies (2); Obesity (2); ophthalmoplegia (2); STAC3 disorder (2); amyotrophic lateral sclerosis (1); asthma (1); autoimmune disease (1); B Cell Lymphoma (1); Bethlem myopathy (1); Brugada syndrome (1); cardiac diseases (1); Chanarin-Dorfman syndrome (1); chronic kidney disease (1); colon tumor (1); congenital myasthenic syndrome (1); Cortisol Excess (1); deafness (1); depression (1); dilated cardiomyopathy (1); dysferlinopathy (1); eccrine porocarcinoma (1); genetic disease (1); head and neck cancer (1); Hyperkalemia (1); idiopathic generalized epilepsy (1).
A further 26 diseases each share a sentence with CACNA1S in 1 paper.